MIR3145 (microRNA 3145)
Synonyms: hsa-mir-3145; mir-3145
Gene: MicroRNA gene on chromosome 6 (138,435,213 to 138,435,294, reverse strand). Ensembl gene ENSG00000266555.
Homologues: Orthologues: chimpanzee MIR3145 (100% identical).